GLP1R (glucagon like peptide 1 receptor)
Diseases named in the same sentence as GLP1R in open-access papers (continued):
Sharing a sentence is not in itself a finding about the gene and the disease.
type 2 diabetes (continued). "As one of the most well-known class B1 G-protein-coupled receptors (GPCRs), the glucagon-like peptide-1 receptor (GLP-1R) is a clinically validated drug target for type 2 diabetes and obesity." (PMID 34145245, 2021). "Sodium glucose cotransporter-2 (SGLT2) inhibitors and glucagon-like peptide-1 receptor agonists (GLP-1RA) were initially approved to improve glycemic control in the treatment of type 2 diabetes." (PMID 32926067, 2020). "Glucagon-like peptide-1 receptor (GLP-1R) plays an important role in glucose homeostasis and treatment of type 2 diabetes." (PMID 32152292, 2020). "Another compound with promising effect in targeting neuroinflammation in PD is semaglutide, a synthetic analogue of glucagon-like peptide 1 (GLP1), which stimulates GLP1R, and it is already used to treat type 2 diabetes." (PMID 33066071, 2020). "Current evidence about the cardiovascular safety of glucagon-like peptide-1 receptor agonist (GLP-1ra) possesses limited generalizability to real-world patients with type 2 diabetes (T2D) in usual practice." (PMID 32534570, 2020). "Glucagon-like peptide-1 receptor agonists (GLP-1 RAs) demonstrated good glycemic efficacy in type 2 diabetes mellitus (T2DM) patients recent years." (PMID 32539783, 2020). "Ligand-specific differences in membrane trafficking of the GLP-1R influence its signalling properties and therapeutic potential in type 2 diabetes." (PMID 33182425, 2020). "Glucagon-like peptide-1 receptor agonists (GLP-1RAs) are effective agents for the treatment of type 2 diabetes (T2D) and obesity." (PMID 32278079, 2020). "Glucagon-like peptide-1 receptor (GLP-1R) is a class B G protein-coupled receptor that plays an important role in glucose homeostasis and treatment of type 2 diabetes." (PMID 32152292, 2020). "The cardiovascular outcome trials (CVOTs) have shown that glucagon like peptide-1 receptor agonists (GLP1RAs) have varying degrees of cardiovascular (CV) safety in patients with type 2 diabetes mellitus (T2DM)." (PMID 32571416, 2020). "During that time, GLP-1R agonists have demonstrated a favorable safety profile in the long-term treatment of type 2 diabetes mellitus." (PMID 33147455, 2020). "Glucagon-like peptide-1 receptor agonists (GLP-1RAs) are currently used to treat obesity/type 2 diabetes." (PMID 32052032, 2020). "To date, cardiovascular outcome studies show that GLP-1 receptor (GLP-1R) agonists reduce atherosclerotic events including myocardial infarction and stroke, and also prevent progression of chronic kidney disease in type-2 diabetic patients." (PMID 32384887, 2020). "The use of agonists of GLP-1R has been demonstrated to be a good therapeutic approach against obesity and type 2 diabetes, by their ability to reach the CNS and modulate metabolic signals, converging in a common molecular mechanism." (PMID 31337027, 2019). "Glucagon-like peptide-1 receptor (GLP-1R) agonists, widely used to treat type 2 diabetes, reduce blood pressure (BP) in hypertensive patients." (PMID 31537818, 2019). "Their receptors, GLP-1R and GIPR, are primarily localized to pancreatic islet cells and implicated in the treatment of type 2 diabetes mellitus (T2DM)." (PMID 31998717, 2019). "Dipeptidyl peptidase-4 (DPP-4) inhibitors and glucagon-like peptide-1 receptor agonists (GLP-1 RAs) are used to treat type 2 diabetes mellitus (T2DM) in adults." (PMID 31870322, 2019). "In recent clinical trials, treatment with glucagon-like peptide-1 receptor agonists (GLP-1 RAs) decreased cardiovascular morbidity and/or mortality in patients with type 2 diabetes at increased cardiovascular risk." (PMID 31586493, 2019). "Till now, the anti-inflammatory effects of GLP-1R agonist have been confirmed in different diseases, such as renal injury, atherosclerosis, type 2 diabetes mellitus, and intracerebral hemorrhage." (PMID 30634956, 2019).
type 2 diabetes (continued). "Glucagon-like peptide-1 receptor agonists (GLP-1RAs) improve glycemia in patients with type 2 diabetes, but heart rate increases have been observed." (PMID 29397532, 2018). "Twenty-seven patients with type 2 diabetes (T2D) were treated with oral hypoglycemic agents, glucagon-like peptide-1 receptor agonist, or insulin." (PMID 30214502, 2018). "Kalra S, Baruah MP, Sahay RK, Unnikrishnan AG, Uppal S, Adetunji O. Glucagon-like peptide-1 receptor agonists in the treatment of type 2 diabetes: past, present, and future." (PMID 29527102, 2018). "Glucagon-like peptide-1 receptor (GLP-1R) is a pharmacological target of incretin therapy for type 2 diabetes." (PMID 29487355, 2018). "Some drugs approved for treatment of type 2 diabetes have been investigated in pediatric T1D, such as thiazolidinediones and glucagon-like peptide 1 receptor agonists, and a growing number of immunotherapy studies are being conducted." (PMID 29860430, 2018). "Combination therapy with insulin and glucagon-like peptide-1 receptor agonists (GLP-1RAs) is important for treating type 2 diabetes (T2D)." (PMID 29688502, 2018). "Glucagon-like peptide-1 receptor (GLP-1R) agonists improve cardiovascular outcomes in patients with type 2 diabetes mellitus." (PMID 30354404, 2018). "Gallwitz B. The future of combination therapies of insulin with a glucagon-like peptide-1 receptor agonists in type 2 diabetes—is it advantageous?" (PMID 29527102, 2018). "We assessed the cost-effectiveness of the glucagon-like peptide 1 receptor agonists liraglutide 1.8 mg and lixisenatide 20 μg (both added to basal insulin) in patients with type 2 diabetes (T2D) in Sweden." (PMID 29408938, 2018). "Exendin-4 is an agonist of the glucagon-like peptide-1 receptor, which is currently prescribed for the treatment of type 2 diabetes and obesity." (PMID 30046063, 2018). "The glucagon-like peptide-1 receptor (GLP-1R) is a key therapeutic target in the management of type II diabetes mellitus, with actions including regulation of insulin biosynthesis and secretion, promotion of satiety, and preservation of β-cell mass." (PMID 28283573, 2017). "Paralogous protein receptors in glucagon-like subfamily, glucagon receptor (GCGR) and glucagon-like peptide-1 receptor (GLP-1R), exhibit divergence in ligands and are clinically validated drug targets for type 2 diabetes." (PMID 28642113, 2017). "Glucagon-like peptide-1 (GLP-1) receptor (GLP-1R) analogues are approved for treating type 2 diabetes, but are known to activate GLP-1R signaling globally and constitutively." (PMID 28947828, 2017). "This reflects the ability to more intensively supplement physiological levels with GLP-1R agonists, rendering them the more powerful approach for treating obesity and type 2 diabetes." (PMID 28733905, 2017). "Glucagonlike peptide-1 receptor (GLP-1R) is an important pharmaceutical target in the treatment of type 2 diabetes (T2D) and has been proposed as a surrogate imaging biomarker for beta cell mass." (PMID 28891030, 2017). "Exenatide (EXT), the first glucagon-like peptide-1 receptor agonist, has been approved as an adjunctive therapy for patients with type 2 diabetes." (PMID 28870261, 2017). "Here, we purified the family B GPCR human glucagon-like peptide-1 (GLP-1) receptor (GLP1R), whose agonists, e.g. exendin-4, are used for the treatment of type 2 diabetes mellitus." (PMID 28609478, 2017). "Incretin-based therapies such as dipeptidyl peptidase (DPP)-4 inhibitors and glucagon-like peptide-1 receptor agonists (GLP-1RA) are now widely used in the treatment of patients with type 2 diabetes." (PMID 27483245, 2016). "An increasing number of patients with type 2 diabetes mellitus (T2DM) are being treated with glucagon-like peptide-1 receptor agonists (GLP-1 RAs), a new class of anti-diabetic agents based on incretin therapy." (PMID 27158818, 2016).
type 2 diabetes (continued). "Even if exenatide has shown encouraging results, several other pharmacological approaches targeting GLP-1R are marketed for type-II diabetes and possibly have a more promising profile." (PMID 26988916, 2016). "Therapeutic intervention to activate the glucagon-like peptide-1 receptor (GLP-1R) enhances glucose-dependent insulin secretion and improves energy balance in patients with type 2 diabetes mellitus." (PMID 26975372, 2016). "In obese type 2 diabetic patients, exenatide and liraglutide (both GLP-1R agonists) treatment for one year led to increased energy expenditure." (PMID 28105413, 2016). "The glucagon-like peptide-1 receptor (GLP-1R) is an important target in the treatment of type 2 diabetes mellitus." (PMID 28035964, 2016). "The GLP-1R is an important target for treatment of type 2 diabetes mellitus, and there are multiple endogenous peptides that activate this receptor." (PMID 27315480, 2016). "This study aimed to investigate the acute renal effects of the glucagon-like peptide-1 receptor agonist (GLP-1RA) exenatide in type 2 diabetes patients." (PMID 27038451, 2016). "Liraglutide was the GLP1R agonist of choice as it improved glycemic control in adult type 2 diabetic patients more effectively than exenatide." (PMID 25890210, 2015). "Glucagon-like peptide-1 (GLP-1) receptor (GLP-1R) agonists, such as exendin-4, have been used in the treatment of type 2 diabetes; they increase glucose-dependent insulin secretion, regulate gastric emptying and reduce food intake and body weight." (PMID 26254578, 2015). "Incretin-based therapy, including dipeptidyl peptidase–4 (DPP–4) inhibitors and glucagon-like peptide–1 receptor (GLP-1R) agonists, has become a popular treatment for type 2 diabetes." (PMID 26439622, 2015). "The glucagon-like peptide 1 receptor (GLP-1r), which has become an important target in the treatment of type 2 diabetes, is emerging as a potential target for such probes, because of its high expression in beta cells." (PMID 25413047, 2015). "Glucagon-like peptide-1 receptor (GLP-1R) agonists represent the best-in-class pharmacotherapies for treating type 2 diabetes." (PMID 25652173, 2015). "Glucagon-like peptide-1 receptor agonists (GLP-1 RAs) were introduced for the therapy of type 2 diabetes about 10 years ago, with exenatide the first drug in the class." (PMID 29632562, 2015). "Glucagon-like peptide 1 (GLP-1) receptor (GLP-1R) agonism, used in the treatment of type 2 diabetes, has recently been shown to increase thermogenesis via the brain." (PMID 26254578, 2015). "Glucagon-like peptide-1 receptor agonists, a new class of anti-diabetic drugs, are widely used in the treatment of type 2 diabetes." (PMID 25213589, 2014). "The question, however, demands further investigations in type 2 diabetes patients treated with GLP1R agonists for longer periods." (PMID 24327600, 2014). "Important early findings in incretin biology include proof-of-concept studies showing GLP-1 infusion improves hyperglycemia in patients with type 2 diabetes and cloning of the GLP-1R cDNA." (PMID 24695667, 2014). "This review is intended to rationally compile the multifactorial cardiovascular effects of glucagon-like peptide-1 receptor agonists available for the treatment of patients with type 2 diabetes." (PMID 25338737, 2014). "GLP-1R (glucagon-like peptide-1 receptor) is a validated therapeutic target for the treatment of type 2 diabetes." (PMID 25330813, 2014). "Our study identified one CpG site showing a small increase in GLP1R DNA methylation in islets from type 2 diabetes patients." (PMID 23879380, 2013). "This review assesses the benefits and risks of adding exenatide twice daily, a glucagon-like peptide 1 receptor agonist, in patients with type 2 diabetes who are currently treated with basal insulin, but have failed to reach their glycaemic goals." (PMID 23061886, 2012).
type 2 diabetes (continued). "Exenatide is a glucagon-like peptide-1 receptor agonist shown to improve glycaemic control in patients with type 2 diabetes (T2DM)." (PMID 22734440, 2012). "The GLP-1 receptor (GLP-1R) is a well-established therapeutic target for the treatment of type 2 diabetes (T2D)." (PMID 21935440, 2011). "GLP-1 receptor agonists analogous to native GLP-1 have thus been developed as an alternative approach to increase GLP-1R activity in the treatment of type 2 diabetes." (PMID 20856794, 2010). "Our aim was to assess the effects of the glucagon-like peptide-1 receptor agonist exenatide on heart rate (HR) and blood pressure (BP) in subjects with type 2 diabetes mellitus (T2DM)." (PMID 20109208, 2010). "Dysesthesia appears to be dose-dependent, occurring more frequently at higher doses and with more potent GLP-1R, whether used for weight management or type 2 diabetes." (PMID 42168638, 2026). "Tirzepatide, a dual glucose-dependent insulinotropic polypeptide and glucagon-like peptide-1 receptor agonist, has shown major metabolic benefits in type 2 diabetes and obesity, but its role in T1D remains unclear." (PMID 42007544, 2026). "Glucagon-like peptide-1 receptor agonists (GLP-1 RAs) are widely used for the management of type 2 diabetes mellitus (T2DM) due to their metabolic and cardiovascular benefits; however, concerns have emerged regarding potential neuropsychiatric effects, including depression." (PMID 42137703, 2026). "In recent years, GLP-1R agonists (GLP-1RAs) have become one of the leading therapeutic options for the treatment of type 2 diabetes mellitus; however, for a long time clinically approved GLP-1RAs were limited to peptide drugs unsuitable for oral administration." (PMID 41976172, 2026). "Moreover, the cardioprotective and β-cell-preserving effects observed in preclinical and clinical studies underscore GLP-1R’s central role as a therapeutic target in type 2 diabetes and its comorbidities." (PMID 41226200, 2025). "Among these, the repurposing of GLP-1r agonists, approved for the treatment of type 2 diabetes and obesity, could represent a valuable solution." (PMID 40789661, 2025). "Glucagon-like peptide-1 receptor agonists, primarily used as a treatment for type 2 diabetes, improve glucose metabolism by stimulating pancreatic insulin secretion, inhibiting glucagon release, increasing glucose uptake in muscle and adipose tissue, and suppressing hepatic gluconeogenesis." (PMID 40429740, 2025). "By stabilizing GLP-1R in its active conformation, exenatide enhances glucose-stimulated insulin secretion, suppresses glucagon release, and slows gastric emptying—actions critical for managing type 2 diabetes mellitus." (PMID 41226200, 2025). "Patients with obesity and co-occurring type 2 diabetes may benefit from an antidiabetic medication known to promote weight loss, such as a GLP-1R agonist or GIP/GLP-1R dual agonist." (PMID 40568728, 2025). "A meta-analysis of overweight and obese patients with or without diabetes demonstrated that GLP-1R agonists improve plasma lipids and glycemic control and induce weight loss, leading to their widespread use in treating type 2 diabetes and obesity." (PMID 40723884, 2025). "Activation of GLP-1R also promotes beta cell survival, inhibits gastric emptying, regulates food intake, and reduces appetite, making it a key pharmacological target for various metabolic disorders including type 2 diabetes (T2D) and obesity." (PMID 40270220, 2025). "Amid the continuously increasing global incidence of diabetes, glucagon-like peptide-1 receptor agonists (GLP-1RAs) have emerged as a cornerstone in type 2 diabetes treatment, demonstrating remarkable efficacy in glycemic control and cardiovascular risk reduction." (PMID 40140925, 2025).
type 2 diabetes (continued). "The aim of this study was to investigate racial and ethnic disparities in the use of sodium–glucose cotransporter 2 inhibitors (SGLT2is) and glucagon-like peptide-1 receptor antagonists (GLP-1RAs) among older adults with type 2 diabetes and cardiorenal conditions." (PMID 39514094, 2025). "We quantified variation in the uptake of sodium-glucose co-transporter 2 inhibitors (SGLT2i) and glucagon-like peptide-1 receptor analogues (GLP-1RA) across sociodemographic, behavioural and clinical characteristics of people with type 2 diabetes (T2D) at high cardiovascular risk." (PMID 40588647, 2025). "Background/Objectives: Semaglutide, a glucagon-like peptide-1 receptor (GLP-1R) agonist, is a well-established pharmacologic agent for inducing weight loss in individuals with obesity and is prescribed regardless of type 2 diabetes mellitus (DM) status." (PMID 40732345, 2025). "The implementation of glucagon-like peptide 1 receptor agonist (GLP-1RA) medications has increased significantly over the past few years due to demonstrated efficacy with both weight loss and improvement in outcomes related to type 2 diabetes mellitus (T2DM)." (PMID 41001395, 2025). "Meta-analyses, mainly derived from studies on patients with type 2 diabetes, found that liraglutide or exenatide treatment increased adiponectin levels and reduced leptin levels, indicating that GLP-1R agonism has concordant effects on the size and secretome of adipose tissue." (PMID 40892365, 2025). "Similarly, the glucagon-like peptide-1 receptor (GLP-1R) is well established as a therapeutic target for type 2 diabetes and obesity, with GLP-1R agonists effectively lowering glucose levels and promoting weight loss." (PMID 41226200, 2025). "Glucagon-like peptide-1 receptor agonists (GLP-1RAs) play a pivotal role in managing type 2 diabetes mellitus (T2DM), obesity, and other conditions, with proven benefits including, but not limited to, weight loss, glycemic control, and cardiovascular protection." (PMID 41164064, 2025). "Many clinical trials have assessed the use of GLP-1R agonists for obesity and type 2 diabetes." (PMID 40494889, 2025). "Organ-protective therapy with sodium-glucose cotransporter 2 inhibitors (SGLT2i) and glucagon-like peptide-1 receptor agonists (GLP1RA) is recommended for people with type 2 diabetes (PwT2D) and cardiorenal comorbidities, yet real-world uptake remains uncertain." (PMID 41567800, 2025). "Likewise, glucagon-like peptide-1 receptor agonists (GLP1-RAs), approved for type 2 diabetes and obesity, achieve weight loss ≥ 5% from baseline in 60%, 85%, and 90% of patients treated with liraglutide, semaglutide, and tirzepatide, respectively." (PMID 40149352, 2025). "Glucagon-like peptide-1 receptor (GLP-1R) agonists are injectable peptide-based therapies that have become a focal point in the medical community due to their significant therapeutic efficacy in type 2 diabetes and obesity treatment." (PMID 41303737, 2025). "While glucagon-like peptide-1 receptor agonists (GLP-1RAs) are well-established in the treatment of type 2 diabetes and obesity, emerging evidence suggests they may also exert protective effects on the liver through the modulation of epigenetic pathways." (PMID 40867230, 2025). "Glucagon-like peptide-1 receptor agonists should be considered for patients with type 2 diabetes; there is strong evidence for their reduction of major adverse cardiovascular events among patients with type 2 diabetes and CVD." (PMID 39801818, 2025). "Sodium-glucose cotransporter 2 inhibitors (SGLT2-I) and glucagon-like peptide-1 receptor agonists (GLP-1RA) have been shown to reduce cardiovascular risk and mortality in patients with type 2 diabetes mellitus (T2D), yet remain underutilized in clinical practice." (PMID 40887578, 2025).